IL33 (interleukin 33)
Diseases named in the same sentence as IL33 in open-access papers (continued):
Sharing a sentence is not in itself a finding about the gene and the disease.
lung carcinoma (continued). "As for IL33, previous studies suggested that it could promote the occurrence and development of lung cancer." (PMID 35211471, 2022). "In conclusion, IL-33 combined with doxorubicin might reduce the cardiac damage and kidney injury observed during the lung cancer treatment." (PMID 35634336, 2022). "ST2L-negative highly metastatic lung cancer cells were found to be insensitive to IL-33." (PMID 35634336, 2022). "Moreover, plasma IL-33 concentrations were increased in the course of the early stage of lung carcinoma and reduced in the advanced stage of disease." (PMID 31652497, 2019). "Moreover, analysis of TCGA and GEO lung cancer expression datasets revealed that higher expression levels of IL-33 mRNA were correlated with longer overall survival of patients suffering from adenocarcinoma of the lung." (PMID 29499051, 2018). "The role of IL-33 in lung cancer progression, however, remains elusive." (PMID 29499051, 2018). "These discrepancies suggest that the role of IL-33 in lung cancer may be context dependent and therefore additional studies evaluating the signaling mechanisms by which IL-33 functions are necessary." (PMID 30205617, 2018). "Recently, IL-33 in circulation was defined as a biomarker for evaluating lung cancer progression." (PMID 29568370, 2018). "Therefore, additional studies are necessary to clarify the contribution of IL-33/ST2 signaling to lung cancer, in particular to NSCLC." (PMID 28119694, 2016). "ST2L-negative high-metastatic lung cancer cells are unsusceptible to IL-33." (PMID 26775708, 2016). "IL-33 expression was also inversely correlated with the stages of human lung cancers." (PMID 26775708, 2016). "In summary, our findings demonstrate that IL-1β, in concert with other unknown co-stimulating factors, induces IL-33 in ST2L-positive low-metastatic lung cancer cells." (PMID 26775708, 2016). "Additionally, lung cancer has a bad prognosis when IL-33 is expressed at a lower level." (PMID 36874133, 2023). "In a murine model of heterotopic lung cancer expressing IL-33, ILC2-deficient mice, which were generated by reconstituting their bone marrow with RORalpha-/- hematopoietic stem cells, showed increased tumor growth and metastasis, suggesting an anti-tumor role for IL-33-activated ILC2 cells." (PMID 37781372, 2023). "While a study reported that IL-33-induced activation of ILC2s may lead to the reduced function of lung NK cells, others found that ILC2s could interact with DCs and T cells to augment the antitumor function in a variety of cancers including lung cancer." (PMID 35634336, 2022). "However, the high level of IL-33 in the tumor tissue of lung adenocarcinoma can lead to relatively longer survival period, thus indicating that IL-33 may play different roles in different types of lung cancer tissue." (PMID 35634336, 2022). "IL-33/ST2 signaling pathway has been implicated in tumor-associated immune response and inflammatory disease of the lung, and IL-33 could significantly promote the migration and invasion of lung cancer cells through alpha serine/threonine-protein kinase (AKT) pathway activation." (PMID 33005178, 2020). "Moreover, in IL-33 transgenic mice injected with melanoma and lung carcinoma cell lines, results revealed significantly increased tumor infiltration cytotoxic CD8+ T lymphocytes and natural killer cells compared to non-transgenic mice leading to cytolysis-mediated cancer cell death." (PMID 33046978, 2020). "The contrasting data about IL-33 levels in patient serum could be both correlated to the rather short half-life of the molecule or to the fact that in some kinds of tumors it is secreted nearby its niche of near the neoplastic mass (i.e., lung cancer)." (PMID 31652497, 2019). "This might explain why lung cancer patients with higher expression levels of IL-33 survive longer." (PMID 29499051, 2018).
lung carcinoma (continued). "While the down-regulation of IL-33 ultimately decreases functionality of MHC-I and reduces immune-surveillance, the overexpression of IL-33 reverses the antigen presentation deficiency in murine metastatice lung carcinomas, and makes the tumour noticeable to both innate and adaptive immune pathways." (PMID 27619158, 2016). "In lung cancer, eosinophils demonstrate complex and context-dependent functions, shaped by chemokines, cytokines, and tumor-derived signals such as CCL11 and IL-33." (PMID 42131323, 2026). "Targeting IL-33/ST2 signaling reprograms TME and potentiates anti-PD-L1 immunotherapy responses in lung cancer, melanoma and CRC." (PMID 40380196, 2025). "In this study, we demonstrated that both CAFs and tumor cells treated with DNA damage-inducing agents secrete high levels of IL-33, which promotes DDR and chemoresistance in lung cancer cells." (PMID 40216748, 2025). "Our study showed that α-IL-33 and α-ST2L blocked the IL-33/ST2L axis and suppressed M2 macrophage polarization to enhance anti-tumor effect of cisplatin in lung cancer." (PMID 38778059, 2024). "In terms of individual molecules, most of them were studied in human cancers, including lung cancer (e.g., AQP1, AQP4, IL33, and PEBP4)." (PMID 35211471, 2022). "Blocking the IL-33/ST2 signaling can serve as a potential lung cancer therapeutic mechanism that can effectively inhibit the proliferation and migration of lung cancer cells." (PMID 35634336, 2022). "We obtained five key genes such as GREM1, MMP11, SPP1, FOSB, and IL33 which were strongly associated with lung cancer in nonsmoking women, which improved understanding and could serve as new therapeutic targets, but their functionality needs further experimental verification." (PMID 34671675, 2021). "Total cellular RNA was extracted from A9+vector, A9+IL-33, and TC1+vector murine lung carcinoma cell lines using Illustra RNAspin Mini Kit (GE Healthcare Life Science)." (PMID 29440650, 2018). "Duplicate arrays were performed with preparations from A9+vector, A9+IL-33, and TC1+vector murine lung carcinoma cell lines." (PMID 29440650, 2018). "Similar effects of chitin and Car/Thy on IL-25, IL-33, and TSLP were seen with H292 human lung mucoepidermoid carcinoma cells and A549 human lung carcinoma cells." (PMID 27463381, 2016). "We found that chitin exposure rapidly induced the expression of three key type 2-promoting cytokines, IL-25, IL-33 and TSLP, in BEAS-2B transformed human bronchial epithelial cells and in A549 and H292 lung carcinoma cells." (PMID 27463381, 2016). "It was previously reported that the combination of IL-33 with PD-1 mAb prolongs the survival of leukemia-bearing mice and PDAC mice and stimulates anti-tumor responses in mouse models of Ret melanoma and orthotopic lung cancer." (PMID 40317004, 2025). "Finally, we assessed IL-33 expression and Rab37+ST2L+CD206+ M2 macrophage infiltration in lung cancer patients with chemotherapy response data." (PMID 38778059, 2024). "Thus far, our results indicated that IL-33 promotes M2 macrophage polarization and an immunosuppressive TME, reducing cisplatin efficacy in lung cancer via IL-33/ST2L/NF-κB signaling and Rab37/ST2L trafficking." (PMID 38778059, 2024). "LL-37 cooperated with IL-33 to increase the phosphorylation of p38 MAPK as well as NF-κB p65 pathways, and augmented IL-6 and IL-1β secretion, thus resulting in the proliferation of lung cancer cells in vitro." (PMID 35634336, 2022). "On the other hand, some studies suggested that it (IL33) could activate NK and CD8+T cells to suppress lung cancer." (PMID 35211471, 2022). "reports that IL-33 treatment enhances ILC2 IL-5 immune response in the lung, thus activating eosinophils that subsequently suppress vital, anti-tumor Th-1 immunity, and lending to increased lung cancer metastasis and mortality." (PMID 34531874, 2021).
lung carcinoma (continued). "IL-33 up-regulates glucose transporter 1 (GLUT1) expression in NSCLC through activation of the ST2 pathway, thereby enhancing glucose uptake and glycolysis and promoting the growth and metastasis of lung cancer cells." (PMID 33988228, 2021). "In detail, patients with lung cancer were reported to not show a statistical difference in the IL-33 levels and some other cytokines, like IL-27 and IL-31, compared to healthy subjects, although the patient’s cohort was small." (PMID 31130612, 2019). "Furthermore, the authors found that IL33 and IL1RL1 transcript levels were inversely correlated with stages of human lung cancers and overall survival." (PMID 28119694, 2016). "We searched the Oncomine database for ST2 (IL1RL1) and IL-33 expression levels in lung cancer tissues and in adjacent normal lung tissues." (PMID 26775708, 2016). "According to our microarray data, IL-33 is down-regulated in the metastatic murine prostate and lung carcinomas (data not shown; unpublished)." (PMID 27619158, 2016). "While many studies have shown a critical role of the IL-33/ST2 signaling in inflammatory lung disease, including respiratory allergy, asthma, and chronic obstructive lung disease, few have investigated the contribution of this pathway to lung cancer." (PMID 28119694, 2016). "However, another study reports downregulation of IL33 and IL1RL1 in human lung cancer tissue and cells, compared to normal tissue and cells." (PMID 28119694, 2016). "In our opinion, there is no doubt that IL-33 has a dual role in lung cancer." (PMID 31130612, 2019). "In the first case, Wang and collaborators showed that the IL-33/ST2 pathway up-regulated membrane glucose transporter 1 in non-small-cell lung cancer cells, enhancing their glucose uptake and glycolysis, thus favoring in vitro outgrowth of human lung cancer and its metastasis in a mouse model." (PMID 30416507, 2018). "Primary lung carcinoma cells, TC1, treated with IL-33-directed siRNAs had a much lower abundance of MHC-I complexes than did controls, whereas the overexpression of IL-33 in metastatic cells (A9) had a higher level of MHC-I production compared to untransfected controls." (PMID 27619158, 2016). "Furthermore, α-IL-33 and α-ST2L treatments increased CD8+ T cell infiltration in the tumor site, which suggests that combination with α-PD-1 may enhance the anti-IL33 therapeutic efficacy in lung cancer." (PMID 38778059, 2024). "In addition, it is reported that IL-33 could promote the differentiation and maturation of DCs, which augmented the antitumor effect of CD8+ T cells and NK cells and inhibited the proliferation of lung cancer cells through affecting MyD88 pathway." (PMID 35634336, 2022). "Notably, the in vitro anti-tumor results indicated that the α-IL-33 and α-ST2L did not directly inhibit cell growth or induce cell death in LLC presumably due to low basal level of IL-33 secretion in lung cancer cell lines without cisplatin treatment." (PMID 38778059, 2024).
chronic obstructive pulmonary disease (52 papers, 2014 to 2026). A chronic and progressive lung disorder characterized by the loss of elasticity of the bronchial tree and the air sacs, destruction of the air sacs wall, thickening of the bronchial wall, and mucous accumulation in the bronchial tree. "IL-33 plays a crucial role in inflammation and is associated with many diseases, such as giant cell arteritis, biliary atresia, and chronic obstructive lung disease." (PMID 24778632, 2014). "Previous studies have reported that increased IL-33 expression in the epithelium contributes to long-term innate immune activity and pathogenesis in diseases such as chronic obstructive pulmonary disease and emphysema." (PMID 40059822, 2025). "In a phase 2a trial, itepekimab, a monoclonal antibody targeting IL‐33, reduced exacerbation rate and improved lung function in former smokers with chronic obstructive pulmonary disease." (PMID 39465143, 2024). "In human chronic obstructive pulmonary disease, increased IL-33 concentrations in lung epithelial cells are related to disease severity." (PMID 36291105, 2022). "In recent years, the alarmin IL-33 has emerged as an important mediator of eosinophilic inflammation in atopic disease and chronic obstructive pulmonary disease (COPD)." (PMID 35082127, 2022). "Efficacy, safety, and tolerability of SAR440340 (anti-IL-33 mAb) is currently under investigation in patients with moderate-to-severe chronic obstructive pulmonary disease (COPD) (ClinicalTrials.gov Identifier: NCT03546907)." (PMID 32194407, 2020). "IL-33, which is known to induce type 2 immune responses via group 2 innate lymphoid cells, has been reported to contribute to neutrophilic airway inflammation in chronic obstructive pulmonary disease." (PMID 33992109, 2021). "Increased level of IL-33 was observed in asthma, chronic obstructive pulmonary disease (COPD), and colitis." (PMID 41155460, 2025). "Evidence of such dysregulation has been observed in chronic obstructive pulmonary disease (COPD), where airway tissue from patients displays increased IL-33 expression." (PMID 39508347, 2024). "IL-33 and its receptor ST2, as well as mast cells and their mediators, have been implicated in the development of chronic obstructive pulmonary disease (COPD)." (PMID 35493481, 2022). "Elevated levels of IL-33 and ST2 have been observed in chronic pulmonary obstructive disease (COPD)." (PMID 38082335, 2023). "Anti-IL-33 and anti-ST2 antibodies are examined in the therapy of various inflammatory diseases, such as asthma, chronic obstructive pulmonary disease (COPD), atopic dermatitis, etc., in the second phase of clinical studies; however, their role in cancer therapy has not been fully investigated." (PMID 37762328, 2023). "Here we show that increased IL33 expression occurs from multiple noncanonical promoters in human chronic obstructive pulmonary disease (COPD), and it facilitates production of alternatively spliced isoforms in airway cells." (PMID 38456508, 2024). "The role of interleukin (IL)-33 in patients with chronic obstructive pulmonary disease (COPD) has not been well elucidated." (PMID 33722239, 2021). "However, recent evidence suggests that IL-33 is secreted via endosomes by epithelial cells in chronic obstructive pulmonary disease, via Toll-like receptors by vascular endothelial cells and via perforin 2 by dendritic cells, suggesting that IL-33 can be produced by cells not undergoing necrosis." (PMID 34498700, 2021). "This is further supported by clinical efficacy data for antibodies to IL-33 and its receptor serum-stimulated 2 (ST2; also named IL1RL1 and IL1R4) that have provided clinical precedence for targeting IL-33 in chronic obstructive pulmonary disease (COPD) and asthma." (PMID 37330528, 2023).
Alzheimer disease (51 papers, 2011 to 2025). A progressive, neurodegenerative disease characterized by loss of function and death of nerve cells in several areas of the brain leading to loss of cognitive function such as memory and language. "As a mediator of inflammatory molecules, IL-33 has also been linked to the pathogenesis of Alzheimer’s disease." (PMID 38694387, 2024). "Fu et al10 showed that IL-33 ameliorates Alzheimer’s disease–like pathology, and Alzheimer’s disease is considered to be a risk factor for osteoporosis." (PMID 39224568, 2024). "IL-33 is also strongly associated with neuroinflammation in age-related diseases including Alzheimer's disease and multiple sclerosis." (PMID 35093936, 2022). "The IL-33 rs7044343 C allele has also been shown to be strongly associated with a diminished risk of Alzheimer’s disease in a study encompassing various populations." (PMID 34177886, 2021). "Human genetic studies reported that a single-nucleotide polymorphism (SNP) in IL-33 is associated with increased risk for the late-onset form of Alzheimer’s disease." (PMID 29379874, 2017). "Recently, studies also reported that IL-33 has been implicated in certain CNS diseases such as Alzheimer disease (AD) and experimental autoimmune encephalo-myelitis (EAE)." (PMID 27699084, 2016). "Genetic variants in IL33 were reported to be associated with decreased risk of Alzheimer disease (AD)." (PMID 24779919, 2014). "This study also demonstrated that 3 polymorphisms within the IL-33 gene resulting in a protective haplotype were associated with risk of Alzheimer's disease." (PMID 21871091, 2011). "Notably, IL-33 has been implicated in neuroinflammation across a range of neurological disorders, including Alzheimer’s disease (AD), Parkinson’s disease (PD), multiple sclerosis (MS), schizophrenia, and central nervous system injury (CNSi)." (PMID 39925809, 2025). "IL-33 is related to pathogenic mechanisms in neurodegenerative disorders such as Parkinson’s disease (PD), Alzheimer’s disease (AD), multiple sclerosis (MS), Huntington’s disease (HD), chronic traumatic encephalopathy (CTE), and amyotrophic lateral sclerosis (ALS)." (PMID 37892176, 2023). "IL-33 has also recently been associated with Alzheimer’s disease (AD) and rheumatic heart disease." (PMID 37686309, 2023). "Moreover, IL-33 polymorphisms modulate the risk of Alzheimer’s disease, with some rare single-nucleotide polymorphisms (SNPs) found to be protective." (PMID 37429945, 2023). "IL-33 expression was shown to be lower in the brains of Alzheimer's disease patients when compared to controls, and additional genetic investigation revealed three variants within the IL-33 gene, indicating a protective haplotype linked with Alzheimer's disease risk in non-APOE e4 carriers patients." (PMID 35224555, 2022). "Moreover, a deficiency for Il33 is associated with neurodegeneration and impaired repair of neurons in aged mice accompanied by memory loss and cognitive impairment, resembling an Alzheimer’s disease-like phenotype, including tau abnormality." (PMID 34716557, 2022). "Moreover, IL-33 has been associated with Alzheimer’s disease, multiple sclerosis, schizophrenia, CNS injury, CNS parasitic infection, and glioma." (PMID 32486265, 2020). "This concept is supported by the important function of IL-33 in CNS development and its association with a variety of neurological diseases, including Alzheimer’s disease (AD) in which genetic variants of Il-33 are associated with increased disease susceptibility." (PMID 27455844, 2016). "Furthermore, it was demonstrated that genetic variants in IL‐33 gene might be associated with the decreased risk of Alzheimer disease." (PMID 31397082, 2019). "Recent evidence has highlighted the crucial role of the IL-33/ST2 pathway in Alzheimer’s disease (AD), Parkinson’s disease (PD), and several other neurological conditions." (PMID 40764944, 2025).